IL1B (interleukin 1 beta)
Diseases named in the same sentence as IL1B in open-access papers (continued):
Sharing a sentence is not in itself a finding about the gene and the disease.
myopia (10 papers, 2021 to 2025). "The genotype under the dominant model of IL1β rs1143627 remained significantly associated with high myopia after adjustment for age and sex (OR = 1.66, 95%CI 1.04–2.67, P = 0.03)." (PMID 41138034, 2025). "In conclusion, our study provides evidence linking inflammation-related gene polymorphisms—particularly in CCL2, TGFβ1, MMP1, and IL1β—to high myopia in children." (PMID 41138034, 2025). "Polymorphisms in IL1β (rs1143627) and IL1RN (rs315952) were associated with high myopia, supporting the role of dysregulated cytokine signaling." (PMID 41138034, 2025). "Accumulating evidence has revealed that there is an increase of pro-inflammatory factors in myopia models and patients, such as upregulation of IL-1β in the sclera and increased IL-6 levels in aqueous humor." (PMID 41222199, 2025). "By suppressing the levels of TNF-α, IL-1β, and IL-6 in human retinal pigment epithelium cells, resveratrol inhibits inflammatory effects to ameliorate myopia development." (PMID 37446088, 2023). "LPIN2 mutations link to increased IL-1β and activated NLRP3 inflammasome and may be related to myopia." (PMID 37965330, 2023). "Previously, we observed rapid and significant changes in choroidal gene and protein expression of the pro-inflammatory cytokines IL6 and IL1β in response to myopic defocus, either during recovery from myopia or following application of +15D lenses to normal chick eyes." (PMID 38390290, 2023). "Animal models of experimental myopia showed that FJE, PVE, and FJE plus PVE treatments inhibited axial elongation, as well as NF-κB, TGF-β, IL-1β, IL-6, IL-8, and TNF-α inflammatory factors and collagen expression." (PMID 39006849, 2024). "Studies have shown that prolonged inflammation can exacerbate myopia by enhancing the expression of inflammatory components such as MMP-2, TGF-β, IL-1β, IL-6, and TNF-α." (PMID 39006849, 2024). "T1DM can decrease accommodation of the lens and ciliary muscles, leading to myopia, and T2DM, an inflammatory disease that leads to elevated IL-1β, IL-6, TGF-β, and TNF-α levels, can also exaggerate myopia progression." (PMID 39006849, 2024). "In conclusion, the intraperitoneal injection of MCC950 can attenuate the progression of myopia in FDM by downregulating the expression levels of NLRP3 and its downstream signaling pathway factors (IL-1β, IL-18, Caspase-1, and MMP-2)." (PMID 37958819, 2023). "This analysis indicated that INFG, TNF, IL1B, EGF, HGF and OSM would be predicted to stimulate recovery from induced myopia (activators)." (PMID 38390290, 2023). "We postulate that the expression of inflammatory markers, including NF-κB, TGF-β, IL-1β, IL-6, IL-8, and TNF-α, may contribute to the chronic inflammatory state observed in myopia." (PMID 39006849, 2024). "In order to study the effect of resveratrol on the PI3K–AKT, MAPK, and NFκB pathways, involved in myopia progression, ARPE-19 cells were incubated with TNF-α, IL-6, and IL-1β, alone and with combinations of these cytokines, for 10 min prior to the 10 min treatment with resveratrol." (PMID 34287272, 2021). "Thus, a vicious cycle develops between continuously induced TNF-α, IL-6, and IL-1β inflammatory responses in the RPE cells that would affect the levels of IL-6, IL-8, and MCP-1 intraocularly, which would promote myopia progression." (PMID 34285659, 2021).
neonatal-onset multisystem inflammatory disease (10 papers, 2011 to 2023). "A previous study demonstrated that monocytes were the predominant IL1β-producing cell population in the peripheral blood of neonatal-onset multisystem inflammatory disease (NOMID) patients." (PMID 37041166, 2023). "Overproduction of IL-1β is associated with a variety of autoinflammatory syndromes, specifically FMF and CINCA syndrome." (PMID 32765981, 2020). "A similar, although more dramatic, acceleration of IL-1β secretion, with early achievement of a plateau, was observed in monocytes from a patient with CINCA syndrome." (PMID 21360512, 2011). "Canakinumab, a fully humanized monoclonal antibody that selectively blocks IL-1β, has been shown to be an effective treatment for CINCA/NOMID syndrome." (PMID 26590045, 2015). "Therefore, we established iPS cells from a patient with CINCA syndrome who did not have the NLRP3 mutation, induced them to differentiate into macrophages, and confirmed the production of IL-1β." (PMID 33535645, 2021).
pharyngitis (10 papers, 2015 to 2025). Inflammation of the throat most often caused by viral and bacterial infections. "Many traditional Chinese medicine formulations exert their therapeutic effects in treating pharyngitis by suppressing the release of inflammatory factors, including IL-6, IL-1β, PGE2, and TNF-α, etc." (PMID 39568590, 2024). "In general, myeloid cells are the primary sources of IL-1β and IL-18 and elevated levels of both cytokines were found locally and systemically in a pharyngitis human challenge trial as well as increased frequencies of circulating monocytes and DCs." (PMID 38408992, 2024). "Moreover, Gancao Jiegeng Shegan Decoction can regulate the levels of cyclooxygenase-2 and PGE2; reduce the serum TNF-α, IL-1β, and IL-6 levels; reduce throat inflammation; and exert expectorant effects." (PMID 38464723, 2024). "Animal experiments showed that CQQN could significantly reduce the expression of TNF-α, IL-1β, IL-6, and IL-17 in the serum of rats with pharyngitis (P < 0.05)." (PMID 35528163, 2022). "In pharyngitis, KHJ reduced pathological damage, downregulated interleukin 1β (IL-1β), interleukin 6 (IL-6), prostaglandin E2 (PGE2), and elevated interleukin 10 (IL-10)." (PMID 41357871, 2025). "MAIT cells are highly activated to release IFNγ, IL-1β, IL-2 and TNF, which are involved in pharyngitis, invasive GAS disease and ARF." (PMID 40276383, 2025).
prostate tumor (10 papers, 1998 to 2024). "IL-1β can also induce the expression of endothelin 1 (ET-1), which is implicated in prostate tumor progression." (PMID 32635472, 2020). "Jun depletion in a Pten-deficient background prevented immune cell attraction which was accompanied by significant reduction of active STAT3 and IL-1β and accelerated prostate tumor growth." (PMID 38811984, 2024). "Microarray-based gene expression analysis of larger sample sizes has shown increased expression of proinflammatory cytokines, including IFN-γ, TNF-α and interleukins (IL-1β, IL-6, and IL-8) in prostate tumor tissues of AA men than CAs14,22." (PMID 37698493, 2023). "Identifying such factors leading to inflammasome activation and maturation of IL-1β and IL-18 will help in understanding the role of inflammation in the prostate tumor microenvironment." (PMID 28663562, 2017). "Also, we found that the expression of IL‐1β was significantly upregulated after castration in Pbsn‐Cre4; Ptenfl/fl; Hi‐Myc prostate tumors." (PMID 37092583, 2023). "Meanwhile, prostate tumors tend to evade antitumor immune cells through the secretion of immunosuppressive factors such as interleukin 1 beta (IL-1β), IL-10, and TGF-β in the TME and thereby induce the differentiation of myeloid cells into myeloid-derived suppressor cells (MDSCs)." (PMID 35892678, 2022). "In RM-9 prostate tumors, IL-1β expression was low in RM-9 tumors in young and old mice." (PMID 34604038, 2021). "Mechanistically, IL-1β can induce prostate tumor progression by several pathways." (PMID 32635472, 2020).
renal dysfunction (10 papers, 2010 to 2025). "Similarly, increased IL-1β in liver and other organs is associated with hepatic injury, renal dysfunction and pulmonary leukocyte infiltration after H/R." (PMID 20735845, 2010). "Among the abundant cytokines, TNFα and IL-1β play more important roles in inflammation-mediated renal dysfunctions." (PMID 28367225, 2017). "Thus, a high serum level of both IL-1β and IL-6 correlated with a low EF (cardiac dysfunction) and with high levels of both creatinine (renal dysfunction) and ALT (liver injury)." (PMID 39559354, 2024). "Interestingly, we also report that a high serum level of IL-1β and IL-6 correlates with a low EF (cardiac dysfunction) and with high levels of both creatinine (renal dysfunction) and ALT (liver injury)." (PMID 39559354, 2024). "Renal dysfunction, based on serum creatinine increase, was associated with an increase in total bilirubin, direct bilirubin, GOT and with a pro-inflammatory cytokine profile including IL-2, IL-1β, IL-17A and IL-8." (PMID 36178979, 2022). "A clinical study further corroborates these findings, showing that AKI patients exhibit elevated serum levels of cf-DNA and MPO-DNA, which correlate with renal dysfunction (elevated Scr and BUN) and pro-inflammatory cytokines IL-1β and TNF-α release." (PMID 41244813, 2025). "Although IL-1β is highlighted in the literature as an extremely pro-inflammatory cytokine present in general cases of renal dysfunction, our findings did not identify increases in serum." (PMID 37999512, 2023). "We demonstrated that urine osmotic pressure, urine specific gravity, I-FABP, IFN-γ, IL-1β, and TNF-α were reduced by 8 weeks of IMP supplementation, indicating that IMP may have potential in preventing strenuous exercise-induced renal dysfunction, increased intestinal permeability, and inflammation." (PMID 32143279, 2020).
septic arthritis (10 papers, 2015 to 2025). "TNF-α, IL-1β, and IL-6 have been indicated as being the main cytokines that lead to severe inflammation that precedes cartilage and bone destruction in septic arthritis." (PMID 40005560, 2025). "The results were consistent with a previous study that indicated that LyeTx I-b decreased IL-1β level in the joint of septic arthritis mice model." (PMID 34572719, 2021). "The study's main findings are that synovial IL-1β levels appear to be a reliable tool to measure the severity and clinical relevance of septic arthritis." (PMID 27688601, 2016). "Synovial concentrations of the proinflammatory markers TNFα, IL-1β, and IL-6 are elevated in the course of disease, in which TNFα was a better indicator to discriminate bacterial arthritis from other inflammatory arthritis." (PMID 27688601, 2016). "In horses with naturally occurring and experimentally induced OA and septic arthritis, increased levels of inflammatory components, such as leukocytes, interleukin (IL)-1β, IL-6, tumor necrosis factor α (TNF-α), and matrix metalloproteinases, has been demonstrated." (PMID 36937015, 2023). "Since intra-articular concentrations of IL-1β characterized the clinical relevance and severity of septic arthritis, the correlations to cytokines with known roles in chondrocyte anabolism or catabolism were analyzed, searching for the interaction between inflammation and cartilage metabolism." (PMID 27688601, 2016). "High neutrophil density indicates inflammatory or septic conditions (e.g., synovitis, infectious arthritis) and creates an unfavorable environment for MSC survival through reactive by-products and cytokines such as IL-1β." (PMID 41157231, 2025). "The co‐expression and localization levels of MCT4, GLUT1, IL‐1β, NLRP3, MMP3, and p‐NF‐κB increased by the 14‐day timepoint in chondrocytes and immune cells in our in vivo model of septic arthritis." (PMID 36354099, 2022). "Moreover, after depleting monocytes with etoposide, lower levels of TNF-α, IL-1β, O2−, H2O2, NO, metalloproteinase-2 (MMP-2), RANKL, and osteoprotegerin were detected, attenuating S. aureus-induced tissue destruction during septic arthritis in mice." (PMID 40005560, 2025). "During septic arthritis pathogenesis, macrophages secrete transforming growth factor-beta (TGF-β), IL-6, TNF-α, and IL-1β, cytokines with significant roles in NF-κB activation and osteoclast differentiation, perpetuating the inflammatory milieu and bone resorption." (PMID 40005560, 2025).
Thrombocytosis (10 papers, 2010 to 2025). Increased numbers of platelets in the peripheral blood. "The excellent response to treatment with the IL-1β receptor antagonist, suggests a key pathogenic role of IL-1β in thrombocytosis as well as in the associated systemic symptoms of inflammation." (PMID 31234906, 2019). "Injecting a few nanograms per kilogram of IL-1β results in an increase of acute phase proteins, plasma IL-6, neutrophilia and thrombocytosis." (PMID 20175886, 2010). "Measurement of IL-1β, IL-6 and Tpo plasma levels at different time points confirmed the etiopathogenetic role of IL-1β in causing the thrombocytosis, while Tpo did not appear to be involved and this explains the excellent response to treatment with Anakinra." (PMID 31234906, 2019). "The results of these measurements confirmed the etiopathogenetic role of IL-1β in causing the thrombocytosis, while Tpo did not appear to be involved." (PMID 31234906, 2019). "TFNα, IL-1β, IL-6, and IL-8 are responsible for atherogenesis; especially TFNα is related to CVD and atherogenesis; IL-6 is related to thrombocytosis; IL-8 related with plaque formation; IL-1β related with vascular inflammation and correlate with atherogenesis." (PMID 39844544, 2025).
arteriosclerosis (9 papers, 2017 to 2023). A vascular disorder characterized by thickening and hardening of the walls of the arteries. "In cell-based experiments, we confirmed that H5 could upregulate the expression of IL-1β and IL-8, which were related to arteriosclerosis." (PMID 34768851, 2021). "HASMC cells are known to produce inflammatory cytokines involving IL-6, IL-1β, and TNF-α during arteriosclerosis activity." (PMID 33841150, 2021). "IL-1β knockdown led to a reduced level of IL-1β and PAPP-A, thus might decrease plaque formation and arteriosclerosis." (PMID 36791122, 2023). "In addition to pro-inflammatory cytokines such as TNF-α, IL-1β, IL-6, and MCP-1, chemokines such as macrophage migration inhibitory factor and CXCL12 play an important role in the initiation and the progression of arteriosclerosis." (PMID 36670934, 2022).
bacterial pneumonia (9 papers, 2011 to 2025). Acute infection of the lung parenchyma caused by bacteria (e.g., Streptococcus pneumoniae, Haemophilus influenzae, Chlamydia pneumoniae, Mycoplasma pneumoniae, and Legionella pneumophila). "We identified that the mutant lacking SasD (S. aureus surface protein D; sasD::Tn) induced reduced levels of cytokines G-CSF, CXCL1, MCP-1, and IL-1β compared to the WT strain during bacterial pneumonia." (PMID 36040164, 2022). "Our study found that UC-MSCs can effectively inhibit the development of bacterial pneumonia, primarily by reducing the number of macrophages and neutrophils and inhibiting the secretion of inflammatory factors IL-1β, IL-6, and TNF-α, thereby suppressing in vivo inflammatory reactions." (PMID 40271073, 2025). "IL-1β and TNF levels were elevated in acute infection with concentrations exceeding those found in patients with bacterial pneumonia." (PMID 35732153, 2022). "Interestingly, SPMs, namely the E series Rv, have also been shown to reduce levels of IL-1β in lung tissue during the combination of ALI and bacterial pneumonia in part by reducing neutrophil accumulation." (PMID 37686333, 2023).
candidiasis (9 papers, 2012 to 2025). Infection with the organism Candida. "Of the cytokines induced, IL-1α, IL-1β, IL-6, IL-10, IL-17A, IL-18, IFN-γ, and TNF-α have been previously shown to play an important role in the pathogenesis of invasive candidiasis in vivo." (PMID 22916017, 2012).
cataract (9 papers, 2012 to 2025). Partial or complete opacity of the crystalline lens of one or both eyes that decreases visual acuity and eventually results in blindness. "Venous blood samples from 104 cataract patients and 100 healthy subjects revealed significantly higher levels of interleukin-6 (IL-6), IL-1β, C-reactive protein (CRP) and tumor necrosis factor-1α (TNF-1α) in the cataract group than in the healthy group." (PMID 39556543, 2024). "This novel observation suggests a suppressive impact of IL-1Ra on IL-1β-mediated induction of inflammation, which may consequently lead to the development of cataracts in FECD eyes." (PMID 38792359, 2024). "H2O2-induced oxidative stress could activate NF-κB signaling and increase NLRP3 expression significantly in human lens epithelial cells via caspase-1 activation and maturation of IL-1β, which contributes to pyroptosis and the development of cataracts." (PMID 34925047, 2021). "Several studies have demonstrated that pyroptosis might have a role in cataract formation and that the levels of pyroptosis markers, such as NLRP3, pro-caspase-1, active caspase-1, GSDMD-N, IL-1β, and IL-18, are significantly increased in the capsule tissues or cells of cataract patients." (PMID 34925047, 2021). "Inflammation is indeed a key factor in the development of cataracts, as evidenced by the increased levels of IL-1, IL-1β, IL-6, and TNF-alpha in the vitreous fluid of cataract patients." (PMID 39556543, 2024). "So, we focused in the present study on evaluation of selected pro-inflammatory cytokines (IL-1β, IL-6, IL-8, IL-17A, and TNF-α), anti-inflammatory cytokines (IL-4, IL-10, and IL-13), and the IL-1 receptor antagonist (IL-1Ra) in the aqueous humor of FECD and/or cataract eyes." (PMID 38792359, 2024). "Inflammatory response by IL-1b and possibly IL-6 may play a role in UVR-B-induced cataracts." (PMID 34024244, 2021).
cerebral aneurysm (9 papers, 2012 to 2023). "Much like TBI, ruptured brain aneurysms also induce an influx of peripheral immune cell infiltration into the brain, and increases in IL1β, IL-6, MCP1, and TNF have been associated with poor outcomes for both." (PMID 31711546, 2019). "Furthermore, previous studies have linked the increased IL-1β expression to early brain aneurysm in pre-clinical mice models, and that IL-1β gene knockout diminishes the occurrence of cerebral vascular ballooning." (PMID 36676165, 2023). "Procollagen types I and III expressions are decreased in cerebral aneurysm walls, possibly due to the activation of the p65 subunit of the NF-kB pathway by IL-1β." (PMID 38137108, 2023). "MCP-1 and IL-1β deficient mice and blocking MCP-1 in rats showed impaired cerebral aneurysm formation and progression." (PMID 38001470, 2023). "The results of this study show that elective cerebral aneurysm surgery is followed by increased IL-6 concentrations in plasma and increased IL-6 and IL-1β concentrations in CSF." (PMID 34472736, 2021). "Specifically, smokers have higher levels of IL-1β, TNFα, and IL-6, all of which significantly contribute to the pathobiology of cerebral aneurysm." (PMID 23316103, 2012). "IL1β acts primarily through activation of NF-κB in VSMC of cerebral aneurysm, reducing the biosynthesis of collagen and promoting apoptotic cell death." (PMID 23316103, 2012). "We have previously found that TNF-α can activate a number of pro-inflammatory and matrix remodeling genes in cerebral vascular smooth muscle cells directly implicated in cerebral aneurysm formation, including: MMP-3, MMP-9, MCP-1, VCAM-1, and IL-1β; and IL-1β, VCAM-1 and MCP-1." (PMID 24739142, 2014). "Sitosterol can treat cerebral aneurysms by reducing the expression of chemokines and inflammatory cytokines TNF-α, IL-8, IL-1β, IL-17, IL-6, and MMP-2/9." (PMID 33149752, 2020). "The primary aim was to determine the effect of adjunctive regional/topical lidocaine anesthesia on perioperative temporal profile of pro-inflammatory cytokines concentrations (IL-1β, IL-6, and TNF-α) in plasma and CSF of cerebral aneurysm patients undergoing elective open surgery." (PMID 34472736, 2021). "Trial will test the hypothesis that lidocaine administration decreases concentrations of IL-1β, IL-6, and TNF-α in plasma and CSF in patients undergoing cerebral aneurysm surgery." (PMID 31626100, 2019).